TNF (tumor necrosis factor)
Diseases named in the same sentence as TNF in open-access papers (continued):
Sharing a sentence is not in itself a finding about the gene and the disease.
Hypertension (continued). "Indeed, we found that ginseng intake decreased the levels of cytokines, including IL-1β, IL-6, and TNF-α, and factors associated with high blood pressure, including ACE activity and angiotensin II." (PMID 32727012, 2020). "IL-6 may even show promise as a biomarker; several studies have proposed increased IL-6 and TNF-α serum levels as independent risk factors for the development of high blood pressure in apparently healthy patients." (PMID 31186952, 2019). "In addition, elevated plasma TNF-α levels strength be helpful to identify the elevated risk of high blood pressure patients with coronary endothelial dysfunction." (PMID 31666827, 2019). "TNF-α, which is a well-known pro-inflammatory cytokine with a wide range of biological effects, has also been reported to be involved in functional crosstalk with angiotensin II that causes adverse left ventricular remodeling and hypertrophy in hypertension." (PMID 29636702, 2018). "Taken together, it suggests that CRP and TNF-α may be one of the factors that predisposes individuals to hypertension." (PMID 26989902, 2016). "Tumor necrosis factor-α (TNF-α) is a proinflammatory cytokine with a wide range of biological effects and has been implicated in the pathophysiology of many cardiovascular diseases, including hypertension." (PMID 26378790, 2015). "Here, we test the hypothesis that HO-1 induction can attenuate the hypertension associated with elevated circulating TNF-α, and then determined the effects of both on pro- and anti-angiogenic proteins in pregnant rats." (PMID 26347650, 2015). "Therefore, we conducted this meta-analysis (MA) to assess the incidence and risk of hypertension of anti-TNF agent in RA patients." (PMID 25860222, 2015). "Additionally, we also find that the use of anti-TNF agent is associated with a significantly increased risk of hypertension when compared to controls." (PMID 25860222, 2015). "In rats, blockade of TNF-α signaling by etanercept partially attenuates the hypertension associated with placental ischemia, and infusion of TNF-α to levels seen in rodents with placental ischemia leads to a hypertensive phenotype associated with increased vascular production of endothelin-1." (PMID 25249978, 2014). "In conclusion our data suggests that circulating pro-inflammatory adipokines, particularly ANG II and, TNF-α, represent important factors associated with a hypertension phenotype and may directly contribute to predicting and exacerbating hypertension risk." (PMID 23251471, 2012). "Whilst the role of TNF-α in hypertension risk appears apparent, it should also be stressed that other adipokines such as leptin, IL6, resistin, plasminogen activator inhibitor 1 (PAI-1) and adiponectin may also have a role." (PMID 23251471, 2012). "Moreover, elevated TNFα levels are associated with increased immune cell infiltration in kidney specimens from T2D patients with renal disorders, although TNFα antagonism attenuates hypertension in several models." (PMID 40868889, 2025). "This is of particular interest, as recent studies suggest that a higher IL-6/TNF ratio is associated with impaired vasodilation, increased arterial stiffness, and elevated sympathetic tone—mechanisms that can contribute to persistent or recurrent hypertension after aortic arch intervention." (PMID 41010423, 2025). "Assuming that inflammation may be the underlying mechanism in the relationship between MASLD and hypertension, we evaluated cytokines (TNF-α, IL-6, IL-10, IL-4, and IL-13) in the liver of patients with morbid obesity, MASLD, and SAH compared to patients without SAH." (PMID 39337863, 2024). "Thus, from findings of the present study it appears that inflammation could be a major triggering factor in the causation of hypertension in diabetic patients, and TNF-α could be the marker of the CV risks in these hypertensive T2D patients." (PMID 36085061, 2022). "Moreover, TNFα deficiency improved endothelial function and cardiovascular injury in hypertension." (PMID 36139783, 2022).
Hypertension (continued). "In summary, AngII-induced hypertension associated with T. cruzi infection may act synergistically to increase TNF and CX3CL1 in the 2K1C rat model, thereby intensifying cardiac inflammatory infiltration and worsening the underlying inflammation triggered by this protozoan." (PMID 29590257, 2018). "However, it is confusing that to what extent treatment with anti-TNF agents for RA might be associated with increasing risk of hypertension." (PMID 25860222, 2015). "TNF-alpha blockers such as adalimumab may cause hypertension, heart failure, atrial fibrillation." (PMID 23970991, 2013). "In the PE rat model, downregulation of GCLM and SNAP23 and upregulation of RHOT2 were significantly correlated with clinical phenotypes such as hypertension and proteinuria, as well as changes in placental inflammatory factor levels (TNF-α, IL-1β, IL-6)." (PMID 41953137, 2026). "Logistic regression analysis identified T0 irisin, T1 irisin, T0 Tumor necrosis factor-α (TNF-α), and hypertension as independent factors associated with the development of POCD (all P < 0.05)." (PMID 41961791, 2026). "The downregulation of IL-10 and upregulation of TNF-α and IL-1β show a sustained inflammatory state, which is consistent with hypertension-driven low-grade inflammation as well as increased production of trimethylamine N-oxide (TMAO) in hypertensive models." (PMID 41515269, 2026). "Increased arginase-1 activity, which can be triggered by ROS, TNF-α, and angiotensin II through AT1R, has been associated with vascular dysfunction in conditions such as hypertension, and acute myocardial infarction." (PMID 40647187, 2025). "Subsequent mediation analysis identified 5 potential mediators, with weight contributing the most at 30.3%, followed by IL-17 (17.2%), TNF (14.08%), coronary atherosclerosis (13.4%), and hypertension (11.6%)." (PMID 39988492, 2025). "TREM2 KO hypertensive mice with Pb exposure exhibited further upregulated proinflammatory cytokines (IL-6, TNF-α) and downregulated anti-inflammatory comparing with C57 mice in the Pb + hypertension group." (PMID 39853035, 2025). "The positive association between hypertension or CVD and GDF15 was mediated 27.9% by TNFR1, 13.6% by IL-6, and 1.9% by TNF-a independently." (PMID 41280118, 2025). "Further, by releasing IL-2 and TNF-α, O3 induces inflammation, which promotes hypertension, coronary ischemia, and the impairment of autonomic control in the lungs and in the circulation." (PMID 40559941, 2025). "Another study investigating AngII-induced hypertension in the context of T. cruzi infection revealed a synergistic effect of hypertension and T. cruzi infection on TNF and CX3CL1 expression, leading to enhanced leukocyte recruitment into cardiac tissue." (PMID 40936920, 2025). "Inflammatory factors secreted by PRAT, such as TNF-α and IL-1β, also play a significant role in the pathogenesis of hypertension." (PMID 40487756, 2025). "Of the seven patients with hypertension, two were treated with anti-TNF-α agents, and five with anti-IL-23." (PMID 40699767, 2025). "Hypertension can activate pro-inflammatory cytokines such as IL-6 and TNF-α, leading to BBB disruption and neuronal damage in conditions such as strokes and TBIs." (PMID 39861166, 2025). "Additional studies showed that anti-TNFα ameliorated hypertension induced by a high-fat, high-fructose diet in rats." (PMID 40868889, 2025). "Our analysis revealed tofacitinib exhibited two positive signals for embolic/thrombotic events and hypertension compared to TNF-α inhibitors." (PMID 40354444, 2025). "Following the elevation of Th cells in the kidneys of F. alocis-treated mice, cytokines produced by T cells, including interleukin-17A (IL17A), interferon-gamma (IFNγ), and tumor necrosis factor alpha (TNFα), play crucial roles in hypertension." (PMID 40396735, 2025). "The levels of inflammatory factors, such as C-reactive protein (CRP) and tumor necrosis factor-α (TNF-α), are positively correlated with hypertension." (PMID 41347150, 2025).
Hypertension (continued). "The TNF-α antagonist etanercept has been shown to prevent angiotensin II (Ang II)-induced hypertension and the increase in vascular superoxide, with related factors potentially modulating Treg differentiation and function." (PMID 40134277, 2025). "Central to this inflammatory cascade are cytokines including interleukin (IL)-6 and tumor necrosis factor-alpha (TNF-α), which are elevated in individuals with hypertension." (PMID 40863231, 2025). "Following investigation via 2 UVMR analyses, IL-17, TNF, hypertension, body weight, and coronary atherosclerosis were selected for calculating their mediating effects." (PMID 39988492, 2025). "This elevation of TNF-α during chronic inflammation aggravates endothelial dysfunction, thus contributing to the initiation and worsening of hypertension." (PMID 40759997, 2025). "VCAM-1 promotes the adhesion and migration of macrophages to the endothelium, leading to the production of various proinflammatory cytokines, including IL-1β, TNF-α, and IL-6, in addition to ROS, which ultimately leads to hypertension." (PMID 40028265, 2025). "Ranked by partial mediation proportion, these modifiable mediators included weight (30.3%), IL-17 (17.2%), TNF (14.08%), coronary atherosclerosis (13.4%), and hypertension (11.6%)." (PMID 39988492, 2025). "Inflammatory mediators of hypertension, such as tumor necrosis factor alpha (TNFα), stimulate the production of reactive oxygen species (ROS) and thereby increase hypoxia-inducing factor (HIF1α), which causes tissue hypoxia." (PMID 40357058, 2025). "This study demonstrates that fecal microbiota transplantation from PE rats induces preeclampsia-like symptoms, including hypertension, renal impairment, and systemic inflammation characterized by elevated IL-1β, IL-8, and TNF-α." (PMID 41459234, 2025). "It is postulated that numerous pro-inflammatory markers are elevated in hypertension such as interleukin-17, interleukin-6, interleukin-1β, tumor necrosis factor-α, and inteurleukin-23." (PMID 41003144, 2025). "In a univariate logistic regression, low adropin (<2.95 ng/mL), higher levels of hs-CRP (≥5.15 mg/L) and TNF-alpha (≥2.61 pg/mL), as well as a presence of hypertension, T2DM, and HFpEF were found as positive predictors for asymptomatic coronary calcification." (PMID 40869134, 2025). "Urinary excretion of TNF‐α has been proposed as a marker of TOD in patients with essential hypertension, as it correlated with urinary albumin excretion and Cornell product, two markers of renal and heart failure, respectively." (PMID 40454610, 2025). "This cascade triggers the release of pro-inflammatory cytokines, including TNF-α, IL-1β, and IL-17, which collectively promote vascular dysfunction, renal sodium retention, and sympathetic overactivity—all key mechanisms driving hypertension." (PMID 41322424, 2025). "PWV was significantly related to plasma hsCRP, TNFα, and IL-6 in untreated patients with essential hypertension." (PMID 40943715, 2025). "In addition, TNF-α causes hypertension by decreasing renal sodium excretion and may cause renal damage through a direct effect inducing renal fibrosis or/and through the intermediate effect of hypertension." (PMID 39867890, 2024). "Inflammatory markers including interleukin (IL)-1β, IL-6, IL-17, interferon-γ, and tumor necrosis factor α (TNF-α) are associated with increased BP, while IL-10 is known to mitigate hypertension by safeguarding renal and vascular functions." (PMID 39769109, 2024). "Blocking TNF-α downstream signaling prevents hypertension andAng II-induced increases in vascular reactive oxygen species (ROS) production." (PMID 39484112, 2024). "The researchers discovered a positive correlation between TNF-α levels and hypertension in chronic CSC." (PMID 38835666, 2024).
Hypertension (continued). "Contrary to this, in our results nebivolol reduced serum TNF‐α levels, this difference in results could be associated with the use of LPS as a stimulator of the inflammatory process in their study, in contrast to the use of a hypertension model with a disease‐derived inflammatory process." (PMID 38504425, 2024). "The production of TNFα can be induced by lipopolysaccharides, angiotensin II, hypertension, and renal failure." (PMID 39394174, 2024). "Together, these animal studies have suggested that TNFα mediates hypertension through renal physiology and sodium homeostasis, and the effect of its inhibition is dependent upon the type of experimented model." (PMID 38256155, 2024). "TNF-α is a pleiotropic pro-inflammatory cytokine that plays a crucial role in various diseases, including hypertension." (PMID 39592923, 2024). "Oyarce and Iturriaga discovered that the mRNA levels of IL-1β, IL-6, and TNF-α were increased in the NTS of rats with hypertension following 21 days of IH." (PMID 38276286, 2024). "Proinflammatory cytokines (e.g., TNF-a and IL-12/23) are shown to be related to renal inflammation and hemodynamics alterations, thus favoring sodium retention and hypertension." (PMID 38496030, 2024). "Progesterone directly suppressed TNF-α-stimulated endothelin (ET)-1 and attenuated TNF-α-induced hypertension, possibly via the suppression of the renal ET-1 system." (PMID 38586585, 2024). "Others demonstrated that mean TNF values in blood serum were significantly higher in patients with hypertension." (PMID 38396488, 2024). "HFpEF patients were observed to have higher circulating IL-6 and IL-8 levels compared to patients with asymptomatic hypertension, and patients with heart failure had higher IL-6 and TNFα levels compared to healthy individuals." (PMID 38256155, 2024). "The increased level of pro-inflammatory cytokines such as interleukin-1 beta and tumor necrosis factor-alpha (TNF-α) has made hypertension a low-grade inflammatory disease (IL-1β)." (PMID 39171117, 2024). "Immune cells in the brain, including microglia/macrophages, are impacted by hypertension, leading to their activation and expression of pro-inflammatory molecules like IL-1b, IL-6, and TNF-a." (PMID 39144717, 2024). "TNF-α is considered to be a key contributor to the pathogenesis of hypertension in pregnancy, and according to our microarray data, the TNF-α pathway is up-regulated in the inflammatory PE3 placentas." (PMID 39389781, 2024). "It is known that γδT lymphocytes synthesize molecules with a confirmed role in vascular wall fibrosis and thus in the development of hypertension such as IL-17, IFNγ, TNFα, or CCL5." (PMID 39195289, 2024). "In fact, renal expression of TNFα was found to contribute to hypertension in Dahl salt-sensitive rats." (PMID 38256155, 2024). "Inexperimental hypertension, Ang II induces chronic inflammation of blood vessels byactivating T cells to produce TNF-α, leading to increased bloodpressure." (PMID 39484112, 2024). "In patients with hypertension, the levels of tumor necrosis factor-α have been shown to be elevated." (PMID 39599656, 2024). "A well‐established connection exists between essential hypertension and key inflammatory markers, including tumor necrosis factor‐alpha (TNF‐α), interleukin‐6 (IL‐6), and C‐reactive protein." (PMID 38504425, 2024). "Accordingly, PGRN, as one of the competitive molecules of TNF-α, is expressed in case of hypertension secondary to higher inflammatory cytokines, especially TNF-α." (PMID 36658641, 2023). "Increased inflammatory mediators, such as interleukin-6 and tumor necrosis factor, are correlated with the onset of cardiovascular disease in hypertension and osteoporosis." (PMID 37754885, 2023). "EL expression is induced by tumor necrosis factor (TNF)-α, interleukin-1ß, and biomechanical forces in vascular endothelial cells by angiotensin II and hypertension in vascular smooth muscle cells and by lipopolysaccharide in macrophages." (PMID 37445857, 2023).
Hypertension (continued). "In our study, we also found that arterial hypertension promoted an increase in Il-6 and TNF-α in bladder tissue." (PMID 36865350, 2023). "Our findings are in agreement with these reports, as serum levels of IL-6, IL-8, IL-10, TNFα were significantly elevated in patients with arterial hypertension." (PMID 37969879, 2023). "Epimedium flavonoids ameliorated hypertension in rats by reducing serum concentrations of pro-inflammatory TNF-α." (PMID 37108810, 2023). "Compared with the control group, patients in the hypertension group exhibited higher levels of inflammatory factors including IL-6, IL-8, and TNF-α." (PMID 36851332, 2023). "Previous studies from our lab and others have shown that TNF can induce oxidative stress, leading to cardiac dysfunction and hypertension." (PMID 36671012, 2023). "IL-6 (p = 0.035), IL-8 (p <0.0001), IL-10 (p = 0.009), and TNF-α (p <0.0001) serum levels were significantly higher in patients with arterial hypertension." (PMID 37969879, 2023). "Inhibiting TNF-α in RUPP rats attenuated hypertension, Endothelin-1, oxidative stress, and NK cell activation." (PMID 36909242, 2023). "Tumor necrosis factor-alpha is a key proinflammatory cytokine mediating angiotensin II-induced renovascular (2K1C) hypertension." (PMID 37582694, 2023). "Activated T cells are able to secrete cytokines, such as tumor necrosis factor-alpha (TNF-α) and interferon-gamma (IFN-γ), which have been linked to kidney damage and hypertension in pre-clinical models." (PMID 37375602, 2023). "Activated MPS within hypertension leads to ROS production and generation of the cytokines IL-1β and TNFα, which is covered in greater detail in this review referenced here." (PMID 36970367, 2023). "Secondly, licochalcone A not only directly inhibited the activation of the TNF-α/NF-κB pathway but also exhibited strong potential in the inhibition of angiotensin converting enzyme (ACE) in hypertension, heart failures and myocardial infarction." (PMID 36713834, 2023). "Hypertension induced the increase in TNF-α, IL-1β, and IL-6 levels in the brain and serum, and CUMS further increased the levels of these pro-inflammatory cytokines." (PMID 36765376, 2023). "The administration of an endothelin type A receptor antagonist in pregnant rats ameliorates hypertension induced by TNF." (PMID 37043097, 2023). "The IL-6 behaved similarly to TNF-α with a significant increase in subjects with hypertension, 235.3 pg/mL (83.1–482.4 pg/mL), p < 0.01 compared to subjects without hypertension, 64.9 pg/mL (50.6–247.9 pg/mL)." (PMID 36671026, 2023). "TNF-α alone induces symptoms of PE in animal models including hypertension, FGR, oxidative stress, Endothelin-1 and AT1-AA in pregnancy." (PMID 36909242, 2023). "Previously, we showed the anti-inflammatory effect of TNF in the brain in Ang II-induced hypertension." (PMID 37034342, 2023). "It was reported that TNF‐α was involved with the development of hypertension and coronary heart disease." (PMID 36562292, 2023). "The lower ratio of PGRN/TNF-α in the cases with hypertension, compared with healthy samples, accordingly suggests the regulation and control of TNF-α through PGRN." (PMID 36658641, 2023). "Normotensive pregnant rats administered with TNF (50 ng/d) between gestational days 14–19 develop hypertension and express elevated levels of renal, placental, and aortic prepro-endothelin-1." (PMID 37043097, 2023). "Silveira-Nunes found that serum levels of tumor necrosis factor and interleukin-6 increased in patients with hypertension, while the relative abundance of Lactobacteriaceae and Ruminococcaceae decreased significantly." (PMID 37293204, 2023). "Dihydrothalidomide, which inhibits TNF-α synthesis, regressed the arterial wall changes in aneurysms induced by hemodynamic stress and hypertension in mice." (PMID 37873057, 2023).